FPR1 (formyl peptide receptor 1)
Diseases named in the same sentence as FPR1 in open-access papers (continued):
Sharing a sentence is not in itself a finding about the gene and the disease.
cancer (71 papers, 2012 to 2026). A tumor composed of atypical neoplastic, often pleomorphic cells that invade other tissues. "Strong epidemiologic evidence showed that loss-of-function polymorphisms of FPR1 are positively associated with poor responses to chemotherapeutic drugs and an earlier mean age of cancer diagnosis also in CRC patients." (PMID 41425092, 2025). "By binding to specific receptors such as FPR1, N-formylphenylalanine can modulate immune cell activity and reduce inflammatory responses, helping to lower the risk of various cancers." (PMID 39011400, 2024). "Cancer patients bearing mutations in FPR1 showed a selective disadvantage with regard to their prognosis." (PMID 36949244, 2023). "In this study, we have identified potent and selective FPR1 antagonists and have studied their effects on cell growth and invasiveness in two cell models of GC, the third cause of cancer-related death." (PMID 37839346, 2023). "Fpr1-deficient DCs from mice fail to localize to cancer cells succumbing to ICD and have reduced antigen presentation ability." (PMID 36010596, 2022). "Thus, when cancer cells lack Anxa1 or when the host is deficient for Fpr1, the anticancer activity of anthracyclines in mice is compromised." (PMID 36429101, 2022). "Results showed that FPR1-deficient (KO) PBMCs (CA and AA) failed, at different levels depending whether the mutation of FPR1 occurs in heterozygosis or homozygous, to interact with treated cancer cells with respect to normal PBMCs (CC)." (PMID 28986543, 2017). "Accordingly, we demonstrated that FPR1 inhibition in human CRC cells in culture increased the intrinsic angiogenic potential of cancer cells." (PMID 41425092, 2025). "Based on the fact that the FPR1 receptor is highly expressed on a variety of cancer cell types but relatively less expressed in normal tissue, FPR1 represents an attractive target for cancer imaging and therapy." (PMID 40940450, 2025). "From a mechanistic point of view, FPR1 exerts a significant anti-cancer effect in CRC models through mechanisms similar to those observed in GC." (PMID 41425092, 2025). "Thereby, the autocrine AnxA1/FPR1 signaling promotes malignant abilities, migration, and proliferation of cancer cells." (PMID 41283264, 2025). "The present review discusses the mechanisms responsible for this specific function of FPR1 in cancer of the GI tract, focusing in particular on FPR1-mediated signal transduction." (PMID 41425092, 2025). "The strong preclinical evidence in various disease models, including cancer, suggest that FPR1 agonism is a promising therapeutic approach." (PMID 41425092, 2025). "The FPR1 expression can predict early cancer and function as a pharmacologic target for innate immune responses; it plays a significant role in phagocyte accumulation and promotes innate immunity." (PMID 37555363, 2023). "In ICD, after plasma membrane permeabilization, the liberation of ANXA1 guides DC to migrate to the proximity of dying cancer cells via a formyl peptide receptor 1 (FPR1)-dependent mechanism." (PMID 36949244, 2023). "Beside this, Huang and collaborators also described that FPR1 signaling pathway is responsible for the transactivation of the epidermal growth factor receptor (EGFR) that would result in cancer progression." (PMID 34571894, 2021). "Our further preliminary investigations, which we will report in due course, reveal similar effects of FPR1 activation in other cancer types." (PMID 33057069, 2020). "In view of this, we also confirmed the expression of FPR1 in cancer cells grown as xenografts in mice by immunohistochemistry (IHC) (PC-3 and DU145 are shown as examples)." (PMID 33057069, 2020). "More recently, FPR1 has been shown to be expressed in different types of cancer and in this context, plays a significant role in their expansion, resistance and recurrence." (PMID 33057069, 2020). "We first determined the protein level expression of FPR1 in various cancer cell lines, using flow cytometry." (PMID 33057069, 2020).
cancer (continued). "Then, by using primary EOC cells, we analyzed the role of uPAR/FPR1 crosstalk enabling cancer cells to adhere onto matrices and mesothelial cell monolayers." (PMID 31703596, 2019). "The results showed that the FPR1/2 peptide not only efficiently delivered cisplatin to cancer cells, which overexpressed FPR1/2 on the surface, but also activated, as a potent immune adjuvant, an immune anticancer response." (PMID 30402082, 2018). "Activation of FPR1 on cancer gastric cells reduced the local angiogenesis and cancer growth, depending on pro-resolving mediators of inflammation, such as metabolic activity of lipoxygenases (ALOX5/15)." (PMID 30250432, 2018). "This gene codes for a 7 transmembrane G-protein-coupled receptor, formyl peptide receptor 1 (FPR1) that senses a ligand emanating from dying cancer cells, annexin A1." (PMID 28986543, 2017). "We firstly examined the expression of FPR1 in these two cancer cells using qPCR and western blotting." (PMID 28724995, 2017). "We characterize the migration of these cells providing a quantitative confirmation of the essential role of FPR1 in cancer chemotherapy response." (PMID 28986543, 2017). "High expression of FPR1 has been detected in various cancers but the function of FPR1 in tumorigenesis is poorly understood." (PMID 27432059, 2016). "A transporter carrying multiple copies of FPR‐1 targeting groups and a PS could potentially combine efficient phototoxicity and selectivity for cancer cells." (PMID 40129407, 2025). "Furthermore, several synthetic low-molecular-weight ligands for FPR1 have been identified and some of these constitute novel promising compounds for the treatment of cancer and other inflammatory disorders." (PMID 40103822, 2025). "Annexin A1 (ANXA1) is a ligand of FPR1 relevant for cancer immunosurveillance." (PMID 37555363, 2023). "In addition, interaction between actively or passively released annexin A1 (ANXA1) and formyl peptide receptor 1 (FPR1) also contributes to anti-cancer immune responses to chemotherapy." (PMID 37153795, 2023). "Over the years, it has become evident that FPR1 also promote cancer progression by regulating the growth, survival, and invasiveness of cancer cells and, as such, they could be a valuable target in cancer treatment." (PMID 37839346, 2023). "The interaction between ANXA1 and FPR1 has been suggested to result in anti‐inflammatory processes in diseases such as cancer, where interactions of these two proteins on murine dendritic cells (DCs) were shown to establish DC/corpse synapses and clearance of dead cells." (PMID 35146757, 2022). "The interaction between ANXA1 and FPR1 was suggested to influence intratumoral DC maturation and T cell‐mediated anticancer immune responses, thus abolishing the efficacy of anthracycline‐based chemotherapy in cancer." (PMID 35770335, 2022). "Furthermore, FPR1 is reported to have a role in regulating or modulating the immune response in cancer and inflammation." (PMID 34239034, 2021). "Similarly, the expression of the ANXA1/FPR1 or FPR3 pair was upregulated from ductal cell-myeloid cell to cancer cell-myeloid cell communication." (PMID 34326696, 2021). "Interestingly, both cancers showed significant correlations of formyl peptide receptors FPR1 and FPR2 with CSF3 and CSF3R." (PMID 33606788, 2021). "More recently, investigations have revealed that FPR1 plays an important role in cancer." (PMID 34012914, 2021). "In this report, OOC experiments in humans and mouse settings were crucial to demonstrate the importance of the integrity of the FPR1/Anxa1 axis to allow immune cell migration and interaction with cancer cells undergoing chemotherapy-induced immunogenic cell death." (PMID 33842539, 2021). "More recently,investigations have revealed that FPR1 also plays an important role in cancer." (PMID 33057069, 2020).
cancer (continued). "Additionally, we observed that the expression of cell death regulators such as CYLD, EZR, VAMP1, ANAX1, and FPR1 was increased in mild hyperthermia treated cancer cells, which was similar to LIUS treated cancer cells." (PMID 31355136, 2019). "It is worth noting that FPR1 activation has a cytotoxic effect in our model and therefore FPR1 antagonism could potentially block a beneficial action in a cancer setting." (PMID 31170199, 2019). "At present, how FPR1 functions in colorectal epithelial cells remains unclear, but our results show that cancer cell migration correlates positively to cell surface expression of FPR1." (PMID 28724995, 2017). "Thus, the innate immune receptor FPR1 could be a regulator of the balance between microbiota, inflammation and cancer in CRC models." (PMID 35808840, 2022). "We hypothesize an OOC scenario in which DAC induces cancer cells to undergo apoptosis, with a concomitant release of apoptosis-dependent chemokines or via the activation of pathways strictly related to cell death such as the FPR1/Anxa1 axis." (PMID 33842539, 2021). "Furthermore, since uPA/uPAR complexes regulate entering of cancer stem cells a dormant state when unable to establish integrin-mediated interactions, we plan to investigate whether FPR1 expression/function is involved in this process." (PMID 31703596, 2019). "This information, together with the docking analysis of the FPR1/RI-3 complex may provide sufficient information for the design of peptide derivatives labeled with therapeutic radioisotopes, to elicit additional cytotoxic activity against cancer cells." (PMID 31434916, 2019). "The rationale of the experiments was to study the interaction between human cancer cells (breast and colon), which were treated with chemotherapeutic agents, and human peripheral blood mononuclear cells (PBMC), which carried different genetic variants of the FPR1 gene." (PMID 28986543, 2017). "Therefore, FPR1 is a potential therapeutic target for the treatment of malignant human cancer." (PMID 27323409, 2016). "Higher expression of HIF1A, ABCA1, FPR1, CD63, and FCN1 was found in cancer compared to healthy state." (PMID 39315092, 2024). "ANXA1 has the role of the homing factor to recruit DCs or their precursors to cancer cells undergoing ICD, through binding to its receptor formyl peptide receptor 1 (FPR1)." (PMID 36429101, 2022). "N‐formyl peptide receptors (FPR1, FPR2, and FPR3) play key roles in the regulation of inflammatory processes, and recently, it was demonstrated that FPR1 and FPR2 have a dual role in the progression/suppression of some cancers." (PMID 34148303, 2021). "The resulting heatmap showed that in the majority of malignancies, TILs were significantly correlated with multiple representative ICD mediators, such as CALR, LRP1, ANXA1, FPR1, TLR3, IFNAR1, PANX1, and P2RX7." (PMID 33299118, 2020). "Our results demonstrate that targeting FPR1 by a selective small molecule antagonist, such as ICT12035, can provide a new avenue for the treatment of cancers." (PMID 33057069, 2020). "For these studies, we chose to focus on two of the most significantly upregulated and novel ligand–receptor pairs: SAA1‐FPR1, because FPR1 expression increased with grade, and RSPO3‐LGR6, because LGR6 has also been noted to be involved in various types of cancers." (PMID 35619544, 2022). "Thus, we investigated the role of FPR1 in CRC cells in order to verify the possibility that it functions as a regulator of inflammation resolution, angiogenesis and cancer." (PMID 35808840, 2022). "Moreover, FPR1 and FPR2 have been shown to play a dual role in the progression/suppression of some types of cancer." (PMID 34148303, 2021). "It follows that inhibiting the activation of FPR1 by ANXA1, may have a potential role as a therapy against a number of cancers." (PMID 33057069, 2020).
cancer (continued). "Similarly, cancer cells undergoing ICD release the cytoplasmic protein annexin A1 (ANXA1), another DAMP that binds to formyl peptide receptor 1 (FPR1) at the surface of DCs." (PMID 33281620, 2020). "Finally, the cited work considered that different expression of FPR1 might be attributed to differences in exposure to luminal formyl peptides, while in the present study both luminal formyl peptides and proinflammatory factors might affect the expression of FPR1 in a cancer environment." (PMID 28724995, 2017). "However, to date no small molecule FPR1 antagonist has ever been investigated as a potential cancer therapy." (PMID 33057069, 2020). "Since SPMs are metabolite of ω3 and ω6 polyunsaturated fatty acids (PUFA), we were able to demonstrate that diet enriched in PUFA could revert the increased angiogenic potential of FPR1-depleted tumors by enforcing SPMs production and counterbalancing the lack of resolution of cancer cells." (PMID 41425092, 2025). "On the other hand, an involvement of FPR1, GPR18 and others in cancer promotion has not been described." (PMID 29861840, 2018).
bacterial infection (18 papers, 2012 to 2025). "The chemoattractant properties of FPR1 have been widely demonstrated; activated FPR1 plays a key role in the directional migration of phagocytes to the site of bacterial infections." (PMID 40103822, 2025). "To further investigate Fpr1’s function in TB pathogenesis, specifically its impact on neutrophils and macrophages in controlling bacterial infection, we first isolated neutrophils from both Wt and Fpr1−/− mice." (PMID 38853986, 2024). "Specifically, ANXA1/FPR1 interactions generally mediate wound closure, particularly in the context of bacterial infections." (PMID 39076982, 2024). "Polymorphonuclear leukocytes (neutrophils, PMN) migrate toward the injury site by detecting mtFPs through formyl peptide receptor 1 (FPR1) to fight/contain bacterial infection and clean up debris." (PMID 37108790, 2023). "Here we report a fluorescent photoaffinity probe for Formyl peptide receptor 1 (FPR1), a critical component of the innate immune response to bacterial infection and a promising target in inflammatory diseases." (PMID 36908701, 2023). "Formyl peptide receptor-1 (FPR1) is a G protein-coupled chemoattractant receptor that plays a crucial role in the trafficking of leukocytes into the sites of bacterial infection and inflammation." (PMID 37839346, 2023). "As a result, FPR1 is critical to phagocyte migration and activation in bacterial infection, tissue injury and inflammation." (PMID 36064945, 2022). "Fpr1/2 is an important component of the innate immune response to defend against bacterial infections." (PMID 34899755, 2021). "The activation of FPR1 and FPR2 can cause a series of signal transduction events, resulting in myeloid cell migration, mediator release, enhanced phagocytosis, transcription of new genes, involvement in host responses to bacterial infection, tissue repair, and wound healing." (PMID 34899755, 2021). "In humans/mice, FPR1/Fpr1 and FPR2/Fpr2 have received much attention for their roles in host defense against bacterial infections." (PMID 31234710, 2019). "FPR1, a member of the chemotactic GPCR-7TM formyl peptide receptor family, is expressed on a variety of leukocytes and is primarily involved in leukocyte migration to the sites of bacterial infections." (PMID 34012914, 2021). "The formylpeptide receptor-1 (FPR1) is a member of the chemotactic GPCR-7TM formyl peptide receptor family, whose principle function is in trafficking of various leukocytes into sites of bacterial infection and inflammation." (PMID 33057069, 2020). "Unlike FPR1 and FPR2, FPR3 does not serve as receptor for fMLF, which represents the established peptide released at sites of bacterial infections and tissue injury." (PMID 40103822, 2025).
inflammation (6 papers, 2016 to 2024). Aberrant reaction of the microcirculation characterized by movement of fluid and leukocytes from the blood into extravascular tissues. "Mice deficient in FPR-1 are protected from bleomycin-induced lung inflammation and fibrosis." (PMID 32102985, 2020). "Overall, these findings suggest that activation of FPR1 signaling is one of key drivers of hyperoxia induced lung inflammation and the ensuing lung injuries, thereby highlighting a potential new therapeutic target for BPD." (PMID 30356317, 2018). "Subsequently, we investigated the contribution of mitochondrial formylated peptides and FPR1 signalling in the pathogenesis of sterile lung inflammation in mice and the influence of FPR1 expression in myeloid and parenchymal cells in this context." (PMID 28469031, 2017). "Together, these data demonstrate that FPR1 warrants further examination and investigation as a potential therapeutic target in sterile lung inflammation." (PMID 28469031, 2017). "Taken together, the protective effects of the FPR-1 gene deletion in CS-induced airway inflammation may depend on the downregulation of the NF-κB pathway." (PMID 33981222, 2021). "In this study, FPR-1 knockout can protect mice against from CS-induced airway inflammation." (PMID 33981222, 2021). "In general, the FPR-1 signaling pathway may have a function on treatment and prevention of CS-induced airway inflammation and relate respiratory disorders." (PMID 33981222, 2021). "In this study, we investigated the role of FPR1 signaling in the pathogenesis of hyperoxia-induced lung inflammation and the ensuing impaired alveolarization and angiogeneisis in mice, and the influences on FPR1 expression with MSC transplantation in this context." (PMID 30356317, 2018). "We investigated whether FPR1 plays a pivotal role in regulating lung inflammation and injuries, and whether intratracheally transplanted mesenchymal stem cells (MSCs) attenuate hyperoxic lung inflammation and injuries by down-regulating FPR1." (PMID 30356317, 2018). "Moreover, acute sterile lung inflammation and injuries induced by mitochondrial formyl peptides and hydrochloric acid were significantly attenuated in the FPR1-/- mice or by a pharmacological FPR1 antagonist." (PMID 30356317, 2018). "Our findings indicate that FPR1 play a critical role in regulating lung inflammation and injuries in BPD, and MSCs attenuate hyperoxic lung inflammation and injuries, but not apoptosis, with down regulating, but not direct inhibiting FPR1." (PMID 30356317, 2018).
cardiovascular diseases (5 papers, 2013 to 2025). "FPR1 can promote the progression of different cardiovascular diseases by activating the MAPKs pathway, generating ROS, and releasing pro-inflammatory cytokines (i.e., IL-1β, IL-6, TNF-α) to promote the inflammatory state." (PMID 37747648, 2023). "Studies suggest that FPR1 may be a promising drug target for cardiovascular diseases, aiding both diagnosis and treatment." (PMID 40630963, 2025).
neurological diseases (3 papers, 2021 to 2023). "Recent studies have shown that FPR1 activation can promote the proliferation and differentiation of nerve cells by activating reactive oxygen species and plays an important role in neurological diseases." (PMID 34580608, 2021).
kidney (2 papers, 2014 to 2025). "The effects of blocking FPR1 on neutrophil function as well as acute rejection were tested in vivo after constructing a mouse kidney transplant model." (PMID 39849390, 2025).
heart disease (1 paper, 2025). "In contrast, a dual FPR1/FPR2 agonist prevented the development of heart disease but failed to correct the lung dysfunction: this was due to an FPR1-mediated recruitment of inflammatory monocytes and concordantly increased numbers of pro-fibrotic CX3CR1+CD11c+SiglecF+MHCIIhi macrophages." (PMID 40181186, 2025).